IL17A (interleukin 17A)
Diseases named in the same sentence as IL17A in open-access papers (continued):
Sharing a sentence is not in itself a finding about the gene and the disease.
asthma (continued). "IL-17F: This cytokine, closely related to IL-17A, engages the same receptors and exhibits comparable pro-inflammatory effects, although its specific role in asthma is not yet fully elucidated." (PMID 40564060, 2025). "Notably, GdT17 cells identified in our model of asthma were enriched for TRDC and pro-inflammatory cytokine IL-17 A, positioning them as major cellular sources of IL-17." (PMID 38317239, 2024). "In contrast, a randomized, double-blind, placebo-controlled study utilizing a humanized anti-IL-17A monoclonal antibody, secukinumab, failed to improve asthma control in patients with severe asthma." (PMID 39194521, 2024). "The interaction analysis showed that combination of both asthma and obesity had significant effects on IL-5, IL-10, IL-17A, IL-33, TNF-α, and leptin, but the effects were not synergistic or additive." (PMID 39902293, 2024). "Another study showed that curcumin, at concentrations of 50, 100, and 200 mg/kg, in comparison to dexamethasone (2 mg/kg), effectively suppressed IL-17A, improved IL-10, and inhibited both the recruitment of eosinophils and mucus overproduction in mice with OVA-induced asthma." (PMID 39263346, 2024). "There are biomarkers useful for various phenotypes of non-eosinophilic and T2 low asthma; Th17 cells may be responsible for associated with a severe asthma phenotype, which is characterized by neutrophilic inflammation and interleukins such as IL-17A, IL-17F, IL-21 and IL-22." (PMID 40980110, 2023). "In the present study, using various human samples (eg, airway biopsy samples, bronchoalveolar lavage fluid [BALF], peripheral blood) and different mouse models of severe asthma, we identify epithelial SIRT6 as an important epigenetic regulator for IL-17A secretion during severe asthma progression." (PMID 38135684, 2023). "Unlike other asthma phenotypes, the IL-17A-related neutrophilic asthma (NA) phenotype exhibits frequent asthma exacerbations or more severe asthma." (PMID 38135684, 2023). "In addition, there was a positive correlation between the H3Cit and IL-17A levels in the asthma serum, proposing a link between NET formation and fibrosis in asthma." (PMID 37626601, 2023). "When isolated peripheral blood mononuclear cells from severe asthma patients are exposed to vitamin D metabolites, these cells do not produce IL-17A." (PMID 37588324, 2023). "By Alician Blue PAS staining, we saw increasing numbers of goblet cells in the asthma groups compared to non-asthma controls, independent of IL-17A administration." (PMID 37443808, 2023). "Thirdly, other studies have shown links between IL-17A and disease severity which leads us to believe that IL-17A plays a role, though not crucial, in the pathogenesis of asthma." (PMID 35371094, 2022). "In this context, the list of proteins and pathways defined in this study may be valuable to design new interventions to specifically target the combinatorial effect of IL-17A/F and TNF-α for the control of severe asthma." (PMID 36517803, 2022). "These dendritic cells secrete IL-4, IL-5, IL-6, IL-13, and IL-17A to drive an enhanced inflammatory response in the airways, suggesting that CNTN1 may act as an inflammatory mediator in the pathology of asthma." (PMID 35492721, 2022). "The protein targets identified in this study will be useful for the development of interventional strategies to target biological processes enhanced by the concurrent presence of IL-17A/F and TNF-α, relevant to chronic respiratory diseases such as steroid-unresponsive severe asthma." (PMID 36517803, 2022). "This mouse model typically reflects eosinophilic mild-to-moderate T2 asthma and does not display a significant increased release of IL-17A or IL-17F." (PMID 35883573, 2022). "A closer look at the study design reveals that the authors took the heterogeneity of the severe asthma population into account, but did not include production levels of IL-17A, that is, the cytokine that should be neutralized by the tested biological." (PMID 35883573, 2022).
asthma (continued). "Hasegawa and colleagues have recently shown that serum levels of IL-17A were significantly different between uncontrolled and well-controlled patients, and that IL-17A levels were correlated with levels of IL-4, IL-25, IL-10, and IFN-γ in patients with uncontrolled asthma." (PMID 35546400, 2022). "This study identifies proteins and signaling mediated by concurrent IL-17A/F and TNF-α exposure in the lungs, relevant to respiratory diseases characterized by chronic inflammation, especially neutrophilic airway inflammation such as severe asthma." (PMID 36517803, 2022). "The results of a phase 2 randomized clinical trial of another anti-IL17A antibody, secukinumab, in patients with inadequately controlled moderate-to-severe T2-low asthma have not yet been published." (PMID 35629272, 2022). "The elevated levels of IL-17A are found in serum, sputum, and bronchoalveolar lavage (BAL) of patients with allergic asthma, and the concentrations of IL-17A are positively correlated with asthma severity at these sites." (PMID 36330091, 2022). "In a mouse obese asthma model, ILC3 stimulated by IL-1β, IL-6, or IL-23 produced IL-17A." (PMID 35626330, 2022). "In ob/ob and HFD-induced obese mice suffering from airway diseases, IL-17A, NLRP3, and ILC3s are essential parts of inflammation, whereas type 2 responses may be unnecessary for an obese asthma phenotype." (PMID 36051916, 2022). "In ACO mice, there was an overlap of asthma and COPD with marked increases of total leukocytes, neutrophils, and eosinophils counts and higher levels of inflammatory cytokines (IL-4, IL-6, TNF-α, IL-1β, IL-17A, and IFN-γ) in BALF." (PMID 33869177, 2021). "IL-17A and IL4 have a potential synergistic effect with TGF-β1 in inducing bronchial EMT, p-Smad3 expression and ERK1/2 signaling pathway activation, and inhibiting E-cadherin mRNA expression in the setting of severe asthma." (PMID 34069141, 2021). "Finally, progesterone stimulates the production of proinflammatory cells and upregulates the expression of cytokines and proteins such as IL10, IL-1β, IL-5, IL-6, IL-22, IL-4, IL-17A, TNFα, and GATA 3 through the regulation of receptors in asthma." (PMID 35096261, 2021). "Indeed, neutralization of both IL-17A and IL-13 inhibited eosinophilia and neutrophilia, mucus hyperplasia, and AHR in a preclinical model of allergen-induced asthma." (PMID 35387016, 2021). "We found that co-culture with epithelium and moMφs significantly increased TSLP mRNA in the asthma group and to a lesser extent or did not change IL-33 and IL-17A mRNA expression in moDCs." (PMID 32842623, 2020). "Interestingly, an increase of IL-17A promotes COPD, asthma and lung cancer, which all have a high prrevalence." (PMID 32000730, 2020). "It was found that IL-17A, IL-17F and IL-22 were increased in peripheral blood mononuclear cells (PBMCs), bronchoalveolar lavage fluid (BALF) and sputum of asthmatic patients, mainly in those with severe asthma." (PMID 33013382, 2020). "An antibody that neutralizes the human receptor for IL-17 (brodalumab, which can neutralize the activities of IL-17A, IL-17F and IL-25) has little effect on patients with mild to moderate asthma in clinical trials and has not achieved satisfactory results." (PMID 32620122, 2020). "Because of the functional overlap between IL-17A and IL-17C and the corresponding receptor complexes IL-17RA/IL-17RC and IL-17RA/IL-17RE, we examined the function of IL-17RE in mouse models of OVA-induced experimental asthma and acute exacerbation thereof." (PMID 32641167, 2020). "Co-culture with epithelium and moMφs significantly increased TSLP in asthma and did not change IL-33 and IL-17A mRNA expression in moDCs." (PMID 32842623, 2020). "Similarly, we found that hSF repressed the transcriptional induction of IL-17A in the lungs of asthmatic female mice (right, *P < 0.05 versus OVA asthma group)." (PMID 30677748, 2019).
asthma (continued). "To demonstrate this hypothesis, we investigated the roles of IL-17A and IL-17F using OVA-induced asthma model mice, generated by knocking out IL-17a and IL-17f (Il-17a−/−Il-17f−/−), and WT mice." (PMID 31852931, 2019). "Patients with severe asthma possess more IFN-γ-positive and IL-17A-positive CD4-positive T cells in BAL cells and increased production of both IL-17A and IFN-γ by CD8-depleted PBMCs from patients with CS-resistant asthma compared with patients with CS-sensitive asthma." (PMID 30736433, 2019). "We next hypothesized that IL-17A and IL-17F were involved in neutrophilic airway inflammation induced by S. commune in OVA-induced asthma model mice." (PMID 31852931, 2019). "Studies have demonstrated the important role of IL-17 pathway in pulmonary diseases, specially in asthma, considering that the overexpression was demonstrated of IL-17A and IL17F in lungs of non-atopic asthmatic patients." (PMID 31168303, 2019). "The upregulated expression levels of IL-1β, IL-6, IL-12, IL-17A, KC, MCP-1 and TNF-α may contribute to airway neutrophilia and asthma exacerbation." (PMID 31889961, 2019). "However, some patients with more severe phenotypes of asthma have increased neutrophils in the airway and BAL fluid that is driven by IFN-γ or IL-17A-mediated pathways." (PMID 30619350, 2018). "Th17 cells produce some pro-inflammatory cytokines, particularly IL-17A, IL-17F, IL-21, IL-22, TNF-α, and GM-CSF, which may have important roles in the reinforcement of severe form of asthma." (PMID 30116273, 2018). "Although significantly higher serum levels of IL-17A have been reported in children with asthma exposed to diesel exhaust particles, we found no increase in IL-17A in BAL fluid." (PMID 27746241, 2017). "In conclusion, our study shows that children with STRA compared with younger controls without asthma have an exaggerated epithelial response to IL-17A, with increased expression of IL-17RA in the airway submucosa and epithelium." (PMID 27746241, 2017). "Epithelial GRO secretion from bronchial epithelial cells was significantly increased in patients with STRA compared with controls without asthma with IL-17A stimulation in combination with budesonide (Fig E1, A)." (PMID 27746241, 2017). "In asthma patients, plasma IL-17A level was negative correlated with adipsin expression (rs = −0.13, P < 0.001)." (PMID 29138487, 2017). "In contrast, our patients with STRA did show enhanced IL-17RA immunoreactivity in submucosa and epithelium as well as increased mRNA expression of IL-17RA and C on stimulation of PBECs with IL-17A when compared with controls without asthma." (PMID 27746241, 2017). "Moreover, the levels of IFN-γ, IL-4, and IL-17A in serum, lung tissue, and BALF of C5aRA-treated RSV-infected asthma mice were also decreased, while the levels of IL-10 were increased." (PMID 29123203, 2017). "In contrast to the data from studies in adults, we have shown levels of IL-17A are not elevated in either the BAL or endobronchial biopsies of children with severe asthma compared to non-asthmatic controls." (PMID 28725641, 2017). "However, the levels of serum IFN-γ, IL-4, and IL-17A levels were increased while the levels of IL-10 were increased by C5aRA treatment in RSV-infected, asthma and RSV-infected asthma mice." (PMID 29123203, 2017). "VEGF was significantly increased in children with STRA compared with controls without asthma when IL-17A and IL-22 were used in combination (Fig E5, A; P = .04)." (PMID 27746241, 2017). "As showed, sera from mice of PBS group, asthma group, severe asthma group and severe asthma plus MS had no IL-17A specific IgG, while mice treated with rMS-Ag85a-IL-17a had high titters of IgG specific to IL-17A in sera." (PMID 26974537, 2016). "These increases of IL-23, MIP-2 and GATA3 were significantly declined in rMS-Ag85a-IL-17a vaccinated group; however, the administration of rMS-Ag85a-IL-17a did not affect RORγt expression in severe asthma." (PMID 26974537, 2016).
asthma (continued). "In viral-induced exacerbation of asthma, however, the part of IL-17A and the interplay between IL-17A and TLR3 activation have not been fully elucidated." (PMID 26418032, 2015). "Previous mechanistic studies in autoimmune models of disease have suggested that pathologic IL-17A production is by IL-17A+IFN-γ+ coexpressing cells, but our data were not consistent with this, rather suggesting separate “immunophenotypes” of SR asthma." (PMID 25772594, 2015). "We demonstrate that the levels of IL-17A synthesis in the PBMC cultures negatively and IL-13 synthesis positively correlate with the absolute change in lung function (FEV1) after 2 weeks of oral prednisolone treatment in our adult asthma cohort." (PMID 25772594, 2015). "IL-2, IL-4, IL-6, IL-17a and TNF-α were reported to be involved in asthma." (PMID 24735374, 2014). "Recently, IL-17A has been shown to play a critical role in airway inflammatory, neutrophil recruitment, airway hyperresponsiveness, and airway remodeling, and it also enhances TH2 cell-mediated eosinophilic inflammation in the airways of patients with asthma." (PMID 23533467, 2013). "Increased levels of IL-17A (or IL-17) protein and messenger RNA were detected in the sputum, bronchoalveolar lavage fluids (BALF), bronchial tissues, peripheral mononuclear cells (PBMCs), and serum from patients with asthma." (PMID 24454477, 2013). "Several studies demonstrated that modifying the expression of IL-17A did not alter the degree of airway remodeling in an experimental mouse model of asthma." (PMID 24454477, 2013). "IL-17A directly enhances ASM contraction through the IL-17RA/RC complex on the basis of a NF-κB/RhoA/ROCK2 signal cascade in murine models of house dust mite-induced and ovalbumin-induced asthma." (PMID 23956759, 2013). "We have shown that the majority of IL-22-producing cells at the site of allergic airway inflammation are CD4+ T cells and that one third of the IL-22-producing CD4+ T cells produce IL-17A, suggesting that some of IL-22-producing CD4+ T cells in a murine asthma model are Th17 cells." (PMID 23577040, 2013). "We also observed that inhibition of neutrophil recruitment with either anti-IL-17A neutralizing antibody, or through genetic deficiency in IL-1R, provided no protection against AHR in our asthma model." (PMID 24069338, 2013). "However, inhibition of IL17A signaling has not panned out to be the therapeutic option it had promised to be for refractory asthma." (PMID 39194521, 2024). "However, we did not see corresponding increase in IL-17A levels in overweight/obesity and asthma group." (PMID 39902293, 2024). "Along with this, we observed a statistically significant positive correlation between systemic IL-26 and IL-17 A concentrations, regardless of whether the analysis included all allergen-sensitized subjects or if it was restricted to only those with asthma." (PMID 38622712, 2024). "However, we were surprised to discover that systemic IL-26 and IL-17 A concentrations did not markedly differ between sensitized children with and without asthma." (PMID 38622712, 2024). "Secukinumab, a fully human anti-IL-17A monoclonal antibody, is now used in rheumatic immune diseases, and a clinical trial has attempted to evaluate its role in patients with asthma not adequately controlled with inhaled corticosteroids but has failed to obtain satisfactory results (NCT01478360)." (PMID 37377958, 2023). "Moreover, NET dismantling with DNase I or IL-17A blocking on NET structures markedly reduces the fibrotic potential of HELFs, suggesting that neutrophils/NETs can be considered both markers of disease severity and active contributors to asthma pathogenesis." (PMID 37626601, 2023).
asthma (continued). "Our findings have revealed that obese asthma patients, despite the basic anti-inflammatory therapy, had elevated levels of inflammatory markers in blood plasma such as leptin, tumor necrosis factor-α (TNF-α), interleukin-2 (IL-2), IL-4, and IL-17a, leukotriene B4 (LTB4), and thromboxane B2 (TXB2)." (PMID 37367676, 2023). "However, a recent study indicated that the increased production of IL-17A by 17β-estradiol and progesterone from TH17 cells may provide a potential mechanism for the increased prevalence of severe asthma in women compared with men." (PMID 35740474, 2022). "However, this modest observed increase in frequency of IL-17A+ non-conventional T cells does not alter asthma severity, as characterized by airway resistance, pro-asthmatic Th2/Th17 cytokine production, pulmonary localization and cell-cell contacts." (PMID 36032166, 2022). "A clinical study demonstrated that a greater number of IL-13-producing T cells and IL-17A-producing CD4+ memory T cells and an increased proportion of IL-5-producing ILC2s are present in the peripheral blood of female patients with asthma compared to those in the peripheral blood of male patients." (PMID 35625578, 2022). "IL-17A is also able to induce the expression of the mucin genes MUC5AC and MUC5B in bronchial epithelial cells in vitro, and enhanced expression of IL-17A correlates with MUC5AC expression in a mouse model experimental asthma after infection with respiratory syncytial virus (RSV)." (PMID 35883573, 2022). "Thus, taken together it may be speculated that the combinatorial effect of IL-17A/F and TNF-α may be a key contributing factor in facilitating neutrophilic inflammation in the lungs in severe asthma." (PMID 36517803, 2022). "In addition to improving Th2-driven asthma phenotypes in mice, we observed that JPH203 could effectively suppress IL-17A production by human T cells." (PMID 35454142, 2022). "Furthermore the anti-IL-17A neutralizing antibody secukinumab failed to improve symptom scores in a small severe asthma study." (PMID 34022896, 2021). "Thus, we speculate that IL-17A and IL-17B interact with various immune factors, specifically TGF-β1, to contribute severity of asthma." (PMID 34221020, 2021). "However, a study of anti-IL17A (brodalumab) in adults with moderate-to-severe asthma showed no improvement in asthma control." (PMID 31284537, 2019). "Taken together, MMPs from IL-17A-mediated inflammation via the AhR activation induced by cigarette smoke exposure may thus contribute to neo-osteogenesis and recalcitrant disease in patients with CRS and asthma." (PMID 31653934, 2019). "The TH17 lymphocytes producing IL-17A and IL17-F cytokines, may have a role on asthma inflammation." (PMID 31168303, 2019). "We found that S. commune, a ubiquitous basidiomycetous fungus in the environment, induces neutrophilic airway inflammation in non-fungus-induced asthma model mice and that IL-17A and IL-17F have central roles in the neutrophilic airway inflammation induced by S. commune." (PMID 31852931, 2019). "Since attenuated production of intracellular IL-17A and IL-10 in mononuclear cells from patients with severe asthma could not be explained by progression of asthma stages, we decided to investigate if the expression levels of IL-10 and IL-17A are correlated." (PMID 30915130, 2018). "As for the monoclonal antibodies brodalumab and secukinumab (both anti-IL-17A), no improving in asthma symptoms has been shown and daclizumab (anti-CD-25) is effective in improving symptoms and function, but it is unclear to which patients it should be addressed." (PMID 29992143, 2018). "However, lack of significant correlation between IL-10 and IL-17A in mild asthma patients suggests different function of these cytokines during initiation of asthma which environment is considered as a causal role." (PMID 30915130, 2018).